IL1B (interleukin 1 beta)
Diseases named in the same sentence as IL1B in open-access papers (continued):
Sharing a sentence is not in itself a finding about the gene and the disease.
cognitive decline (continued). "Since neuroinflammation was closely related to cognitive decline after surgery, the levels of the proinflammatory cytokines IL-6 and IL-1β in the hippocampus were examined 24 h after tibial fracture surgery by ELISA." (PMID 31011286, 2019). "Overall, neuronal dysfunction and subsequently cognitive decline is perpetuated by inflammatory cytokines, such as IL-1β, IL-6 and TNF-α." (PMID 30374291, 2018). "TNF-α and IL-1β as pro-inflammatory cytokines, have been related to the cognitive decline characteristic of AD and proposed to be valuable biomarkers for this disorder." (PMID 25586060, 2016). "Additional inflammatory events in AD patients were associated with elevated baseline levels of TNFα and IL-1β and with an increased rate of cognitive decline over a 2 or 6-month period." (PMID 27555812, 2016). "Extensive research has found that pro-inflammatory cytokines including IL-1β, IL-6 and TNF-α are strongly associated with cognitive decline and motor retardation particularly amongst elderly populations." (PMID 21799922, 2011). "Recently we demonstrated that decreasing a key neuroinflammatory cytokine IL-1β in the hippocampus of aged rats reversed the age-related cognitive decline and increased neurogenesis in the age rats." (PMID 20463965, 2010). "However, only the elevated IL-1β serum level of rs1143627G/G corresponded to the cognitive decline of rs1143627G/G carriers." (PMID 40636929, 2025). "Lowered SIRT1 levels in microglia upregulate IL-1β, leading to cognitive decline in mice with age." (PMID 40363789, 2025). "Opioids may induce cognitive decline through neuroinflammation, increasing hippocampal inflammatory markers (IL-1β, IL-6, TNFα) observed in animal studies." (PMID 40657909, 2025). "The hippocampus, a region pivotal for memory and cognitive function, demonstrated a particularly pronounced negative association with IL1β and T-tau levels, highlighting the link between inflammation, neurodegeneration, and cognitive decline." (PMID 39109268, 2024). "Notably, IL-1β or IL-6 appear upregulated in AD and other neurodegenerative disorders and are correlated with cognitive decline." (PMID 37187754, 2023). "Serum levels of cytokines, such as IL-1β, TNF-α, and IL-10, were higher in PD patients than age-matched non-PD controls; higher TNF-α levels were associated with a faster rate of motor decline and higher IL-1β levels with a faster rate of cognitive decline." (PMID 36832181, 2023). "The cognitive decline in the aging process is regulated by the increased expression of caspase-1, a protein that regulates the maturation and secretion of interleukin (IL)-1β and IL-18, and decreased expression of BDNF, a protein that improves synaptic connectivity." (PMID 34526890, 2021). "A recent meta-analysis showed a significant difference between the level of inflammatory markers (such as IL-6, IL-1b, sTNF-R1 and 2) during cognitive decline, describing in particular an increase in their level in MCI and AD patients (compared to controls), both in CSF and blood." (PMID 33986423, 2021). "Therefore, we suggested here that AT2 receptor activation reduces RAGE expression possibly by attenuating oxidative stress and MCP-1/IL-1β-mediated inflammation in the cerebrovasculature and thus contributing to inhibition of cognitive decline." (PMID 32264971, 2020). "The presence of systemic infections and increased blood (plasma or serum) concentrations of cytokines including interleukin 1β (IL1β), interleukin 10 (IL10), interleukin 6 (IL6), and tumour necrosis factor α (TNFα) have been associated with sAD and predict cognitive decline." (PMID 30902060, 2019). "In line with this, the whole‐brain levels of the pro‐inflammatory cytokines IL‐1β and TNF‐α, which have both been associated with the progression of Aβ deposition, neurodegeneration, and cognitive decline in AD, were reduced in APP/PS1‐Stat3KO compared to APP/PS1‐Stat3WT mice." (PMID 30617153, 2019).
cognitive decline (continued). "Functional inhibition of IL-1β could mitigate the neuroinflammation, and peripheral TNF-α blockade could reduce the release of IL-1β and prevent neuroinflammation and postoperative cognitive decline." (PMID 30501622, 2018). "Increases in IL-1β levels lead to cognitive decline, in particular in hippocampal-dependent tasks." (PMID 28347403, 2017). "AD patients who have suffered from an infection also have a greater rate of cognitive decline than patients without infection, a difference linked to increased levels of serum IL-1β." (PMID 28284226, 2017). "Indeed, blocking IL-1β significantly reduced neuroinflammation, slowed down cognitive decline and attenuated tau pathology in transgenic mouse models of AD." (PMID 27555812, 2016). "Our data suggest that prolonged MV further aggravates cognitive decline after surgery that may stem from upregulation of hippocampal IL-1β, IL-6 and TNFα, partially via activation of gliocytes in surgical mice." (PMID 25887955, 2015). "Prolonged MV after surgery further aggravates cognitive decline that may stem from upregulation of hippocampal IL-1β, IL-6 and TNFα, partially via activation of gliocytes in the surgical mouse hippocampus." (PMID 25887955, 2015). "IL-1β and IL-18 are elevated in the AD brain and have been hypothesized to contribute to neurodegeneration and cognitive decline in AD." (PMID 22824372, 2012). "Further studies are needed to determine whether the NLRP1 inflammasome-induced activation and increased IL-1β and IL-18 observed in our study influence deficits in synaptic transmission leading to cognitive decline." (PMID 22133203, 2011). "Similarly, this study showed a notable decline in IL-6, IL-1β, and TNF-α levels upon OPB administration at both high and low doses, indicating the potential of OPB to mitigate neuroinflammation associated with learning ability and cognitive decline." (PMID 41557677, 2026). "Additionally, we explored whether individual genetic susceptibility, gene-environment interactions, and the peripheral pro-inflammatory factor IL-1β play a mediating role in cognitive decline." (PMID 40636929, 2025). "Moreover, P. gingivalis periodontal infection could cause cognitive decline by releasing proinflammatory cytokines, including tumor necrosis factor-alpha (TNF-α), interleukin (IL)-6, and IL-1β, in the brain." (PMID 40612448, 2025). "This indicates that IL1β expression might impact brain morphology through processes related to neurodegeneration and might predict a decrease in the hippocampal volume in patients with cognitive decline." (PMID 39109268, 2024). "In current study, elevated levels of IL-6, IL-1β, and TNF-α were positively associated with poorer cognition, especially in aged LPS and LPS-EE mice, demonstrating that increased systemic inflammation is closely related to cognitive decline during the accelerated aging." (PMID 36479357, 2022). "Moreover, HMGB1 suppression could decrease proinflammatory cytokines (TNF-α, IL-1β, and IL-6), attenuate hippocampal atrophy, and improve cognitive decline." (PMID 32245271, 2020). "Therefore, a better understanding of IL-1β levels and autophagy status in AD brains according to the stage of the disease would allow improved targeting of anti-IL-1β and pro-autophagic therapies to reduce cognitive decline." (PMID 24330807, 2013). "Thus, aging processes stimulate activation of the NLRP1 inflammasome and secretion of IL-1β and IL-18 that may contribute to age-related cognitive decline in the growing elderly population." (PMID 22133203, 2011). "Emerging evidence highlights maladaptive microglial activation, chronic cytokine signaling (including IL-1β, TNF-α, and IL-6), and hypothalamic-pituitary-adrenal (HPA) axis hyperactivity as pivotal contributors to neuronal damage and cognitive decline." (PMID 41907842, 2026).
cognitive decline (continued). "This process enhances the production of inflammatory mediators such as IL-1β, IL-6, IFN-γ, TNF-α, CCL2, GMF, NO, and ROS, ultimately driving inflammatory responses and cognitive decline in neurodegenerative diseases." (PMID 40556958, 2025). "Studies indicate that glial cell-derived inflammatory cytokines (e.g., IL-1β, TNF-α) trigger neuronal apoptosis through modulation of Bcl-2 family proteins and caspases, ultimately driving cognitive decline." (PMID 41291751, 2025). "However, peripheral blood IL-1β levels do not mediate this association with cognitive decline." (PMID 40636929, 2025). "Proinflammatory cytokines, such as IL-1β and TNF-α, have been reported to induce neuroinflammation and neurotoxicity in the brain and result in cognitive decline." (PMID 38191451, 2024). "Inhibition of NF‐κB can reduce the expression of pro‐inflammatory cytokines (such as IL‐6, IL‐1β, and TNF‐α) and increase the expression of BDNF, thereby ameliorating the cognitive decline of diabetic mice." (PMID 37864452, 2024). "This study highlights the relevance of inflammatory markers such as NLR and PLR in reflecting cognitive decline in PSP patients, with IL-1β potentially playing a protective role in cognitive function." (PMID 39684921, 2024). "In line with these previous studies, the results showed that the levels of IL‐1β, IL‐6, and TNF‐α were increased in the hippocampus of the mice exposed to CSD, which contributed to the observed cognitive decline." (PMID 38688894, 2024). "In line with the observed cognitive decline, significant increases in IBA1 and GFAP immunofluorescent intensity, as well as IL-1β expression were also observed in the APN-KO mice." (PMID 39415089, 2024). "We found by RT-PCR an increase of the expression of mRNA for IL-1β and IL-6 as well as for IFN-γ, pointing to these cytokines, as targets for modulation in cognitive decline." (PMID 37187754, 2023). "Changes in serum levels of IL-6, IL-1β, and TNF-α reflective of systemic inflammation and their correlation with cognitive decline during accelerated aging were similar to those of hippocampal NGPF2." (PMID 36479357, 2022). "These IL-10(-/-) mice also produce more pro-inflammatory cytokines IL-1β, IL-6 and TNF-α in the plasma, suggesting IL-10 inhibits cognitive decline via its propensity to mitigate inflammation." (PMID 35308288, 2022). "IL-1β can suppress BDNF-dependent synaptic plasticity and cognitive decline through disturbing the BDNF signaling pathway." (PMID 32425784, 2020). "Reports demonstrate that inflammatory responses mediated by Aβ peptides in the brains of AD were significantly elevated, such as IL-1β and TNF-α, which is believed to mediate neuronal injury and finally, cognitive decline." (PMID 25586060, 2016). "In the control group, there were bivariate correlations between IL‐1β, IL‐6, and IL‐8 and lower MMSE scores and between IL‐13 and slower rate of cognitive decline (albeit at a significance level of P < 0.05 and notwithstanding correction for multiple testing)." (PMID 26999434, 2016). "Research conducted by the world-renowned pediatric sleep expert Dr. David Gozal and others indicates that chronic fragmented sleep can lead to cognitive decline, increased expression of inflammatory markers such as NF-κB, TNF-α, and IL-1β, as well as heightened activation of microglia." (PMID 40893780, 2025). "In addition, increased levels of inflammatory markers like IL-1β, IL-12, TNF-α, CRP, low CSF and serum BDNF, and altered adipokines are observed in individuals exhibiting both cognitive decline and depressive symptoms." (PMID 40807098, 2025). "The literature has shown that chemotherapy directly results in an upregulation of various well-known pro-inflammatory mediators, such as IL-1β, TNF-α, MCP-1, IL-6, etc., which contribute to symptoms including but not limited to fatigue, peripheral neuropathy, and cognitive decline." (PMID 38731449, 2024).
cognitive decline (continued). "The extent of the elevation of proinflammatory cytokines (IL-1β, IL-6, TNF-α, etc.)in both the central nervous system and the systemic circulation after surgery may relate to the degree of cognitive decline." (PMID 32214903, 2020). "Moreover, IL-1β, TNF-α production and an increase in the apoptosis can reduce adult hippocampal neurogenesis and produce the age-related cognitive decline." (PMID 32059688, 2020). "The proinflammatory cytokines, such as interleukin 1β (IL-1β) and tumor necrosis factor α (TNF-α), have been reported to play an important role in mediating surgery-induced systemic and central inflammation, ultimately resulting in cognitive decline." (PMID 29249869, 2017). "In addition, recent meta-analyses found relationships between higher baseline IL-6 but not TNFα and steeper cognitive decline, with less published research on IL-1β levels and longitudinal cognitive change." (PMID 39055623, 2024). "Devising treatments, such as those targeting IL1β that could “reset” the extracellular environment to a non-inflammatory state, could be of benefit when seeking to prevent cognitive decline." (PMID 31103036, 2019). "However, evidence that multiple serum and CSF proinflammatory cytokines and chemokines, including IL-2, IL-1β, IL-6, IL-10 and IFN-γ, decline over time and may be undetectable in AD suggests that related topic study outcomes can vary with disease stage and cognitive decline." (PMID 37760836, 2023). "EE has also been shown to decrease IL-1β and CD68 expression in the hippocampus, as well as prevent cognitive decline in aged mice, even in the absence of running wheels." (PMID 35112705, 2022).
Hepatic steatosis (133 papers, 2010 to 2026). Steatosis is a term used to denote lipid accumulation within hepatocytes. "In primary hepatocytes, IL‐1β is associated with triglyceride and cholesterol accumulation and the development of hepatic steatosis and lipid droplet formation." (PMID 36637998, 2023). "Our results indicate that elevated hepatic LCN2 and IL-1β are closely associated with hepatic insulin impairment, hepatic steatosis, and excessive lipid circulation, consistent with previous reports." (PMID 31892368, 2019). "Another mRNA downregulated in gastric tissue of patients with high grade hepatic steatosis encodes for Interleukin 1 beta (IL1B), an inflammatory cytokine with anorexigenic function." (PMID 24716593, 2014). "In patients with high grade hepatic steatosis, Interleukin 1 beta encoding gene with anorexigenic function, IL1B was downregulated." (PMID 24716593, 2014). "HF diet feeding, a diet model for obesity and hepatic steatosis, results in severe steatohepatitis in IL-1 receptor antagonist-deficient mice, suggesting that IL-1β plays an important role in NASH." (PMID 21274430, 2010). "In addition, an association between the development of hepatic steatosis and higher serum IL-1β levels and higher adipose tissue was observed in women." (PMID 38732626, 2024). "TNF-α could induce SREBP1 expression, resulting in hepatic steatosis; IL-1β and IL-6 are involved in hepatic steatosis and inflammation, which causes hepatic disease." (PMID 35409071, 2022). "Furthermore, the IL-1β deficiency mice exhibited less hepatic steatosis and intact insulin sensitivity." (PMID 31736870, 2019). "In agreement with the decreased hepatic inflammation observed in clodronate-treated mice, caspase-1-deficient mice (that lack IL-1β expression) exhibit attenuated diet-induced hepatic steatosis and significant decreases in hepatic lipogenic gene expression compared with wild type control mice." (PMID 25216251, 2014). "Interestingly, they found that the incidence of steatohepatitis was correlated with serum levels of the inflammatory markers monocyte chemoattractant protein (MCP), TNF-α, and IL-1β, which highlights the association between systemic inflammatory status and fatty liver." (PMID 37434233, 2023). "Given the observed association between SHP nuclear localization, hepatic steatosis, and inflammation in MASH, we examined SHP nuclear localization following exposure to excess palmitic acid (PA) and IL-1β, alongside the canonical SHP inducer, CDCA." (PMID 41438338, 2026). "In our study, CEL significantly decreased both the liver inflammatory score and pro-inflammatory gene expression (Tnfa and Il1b) at the end of week 16, similar to that in various other studies with mouse models of fatty liver." (PMID 39968178, 2025). "Reduced expression of hepatic inflammatory cytokines (TNF-α, IL-1β, IL-18) and improved hepatic steatosis; decrease in body weight as well." (PMID 40893881, 2025). "It has been shown that ellagic acid can significantly down-regulate the levels of liver inflammatory factors NF-κB, TNF-α, IL-1β, and IL-6 in mice with fatty liver disease induced by AKT gene transfection." (PMID 39877634, 2025). "Both GW4869 and Imip treatments resulted in a significant suppression of IL-1b and IL-6 gene expression, reinforcing the anti-inflammatory effects of inhibiting sphingomyelinase pathways in the context of hepatic steatosis." (PMID 38474427, 2024). "It was characterized by a reduction in dysbiosis, changes in BA metabolism, reduced Il-1β secretion, and alleviation of hepatic steatosis." (PMID 39396247, 2024). "IL-1β is directly involved in IL-1β/TNF-induced hepatocyte necrosis, promoting hepatic steatosis, with positive feedback amplification of inflammation-induced IL-1β and TNF-α." (PMID 38145041, 2023).